BRCA1 (BRCA1 DNA repair associated)
Diseases named in the same sentence as BRCA1 in open-access papers (continued):
Sharing a sentence is not in itself a finding about the gene and the disease.
breast cancer (continued). "Among 2272 BRCA1 and 1605 BRCA2 mutation carriers without a previous diagnosis of cancer or RRM, 269 BRCA1 and 157 BRCA2 mutation carriers were diagnosed with breast cancer during follow-up (mean follow-up time 5.4 and 4.9 years for BRCA1 and BRCA2, respectively)." (PMID 31948486, 2020). "In fact, in PRMT1-silenced breast cancer cells, BRCA1 did not accumulate in the nucleus after IR." (PMID 32764667, 2020). "In addition, BRCA1 may stimulate GADD45A-mediated nucleotide excision repair and DNA demethylation in breast cancer." (PMID 32456160, 2020). "We selected four breast cancer cell lines (MCF7, SKBR3, BT474, and BT20), among which BT20 is a cell line with negative tests of estrogen, progesterone, and excess HER2, and without BRCA1 mutation." (PMID 32175684, 2020). "BRCA1 and BRCA2 germline pathogenic variants were found in 7.3% of the IBC patients, 6.3% had a mutation in other cancer genes (PALB2, CHEK2, ATM and BARD1), and 1.6% had a germline pathogenic variant in other genes not related with breast cancer." (PMID 32075053, 2020). "Recent evidence suggests that BRCA1‐related breast cancer is driven by aberrant RANK/RANKL signalling in BRCA1 heterozygous luminal progenitor cells, coupled with increased DNA damage/defective DNA repair in these cells, resulting in development of basal breast cancers." (PMID 32022473, 2020). "Functionally, it has been shown that ID4 may exert similar inhibitory effects on BRCA1 and estrogen receptor alpha (ERα) gene expression, and, conversely, BRCA1 and ERα may demonstrate redundancy in inhibiting ID4 gene expression in breast cancer cells and tissues." (PMID 32054109, 2020). "Finally, the proportion of bilateral/contralateral breast cancer in the individuals of our cohort (BRCA1 positive: 6 of 13, controls: 6 of 21) did also not differ significantly from the previously reported ones (44.1 and 17.2%, respectively)." (PMID 32727387, 2020). "Our analysis identifies several well-known disease-related genes that are not identified by GWAS, including BRCA1 in Breast Cancer, Amyloid Precursor Protein (APP) in Alzheimer’s Disease, INS in A1C measurement and Type 2 Diabetes, and PCSK9 in LDL cholesterol, amongst others." (PMID 32678846, 2020). "Although no specific patterns of CNAs have been reported in breast cancers with biallelic BRCA1/2 inactivation, these observations led us to hypothesize that specific genomic rearrangements caused by HR deficiency could cause characteristic CN changes." (PMID 33067557, 2020). "This is the first study performed in Kenya to determine the cause of familial breast cancer in patients using WES, which allows for extended data analysis beyond BRCA1/2 at no additional cost in patients who experience treatment failure or medication side effects." (PMID 32231682, 2020). "Interestingly, over half (59.1%, n = 143/242) of the female BRCA1/2 PV carriers not meeting BRCA1/2 testing criteria had a personal history of breast cancer." (PMID 31406321, 2020). "Furthermore, no study has explored the epigenetic modifications of BRCA1 sporadic breast cancer in Pakistan yet." (PMID 32856871, 2020). "Maybe they can grasp this’ – 49-year-old female, BRCA1 PV/LPV carrier, with breast cancer." (PMID 33110458, 2020). "Healthy BRCA1 mutation carriers and non-carriers showed a similar level of γ-H2AX nuclear foci after exposure to radiation, indicating γ-H2AX nuclear foci assay is not likely able to distinguish women at a high risk of hereditary breast cancer." (PMID 33013205, 2020).
breast cancer (continued). "BRCA1 also interacts with GADD45A (growth arrest and DNA damage-inducible protein GADD45 alpha) that may target NER machinery to actively demethylate genome sites in order to change the expression of genes that may be important in breast cancer." (PMID 32013256, 2020). "However, the frequencies of these twenty mutant alleles of BRCA1/2, CHEK2, PALB2, NBN, and RECQL have not been measured in a large series of early-onset breast cancer patients from Poland." (PMID 32824581, 2020). "This is supported by the fact that DNA hypermethylation at the promoter regions of the BRCA1 gene is associated with its downregulation in nonfamilial breast cancer and that inhibition of DNMT activities can prevent the development of breast cancer." (PMID 31963223, 2020). "The outcome of breast cancer in BRCA1 carriers and noncarriers was comparable." (PMID 32322271, 2020). "Also, in contrasting the incidence of breast cancer between BrCa1 carriers and non-carriers, the amount of disease due to the gene is estimated." (PMID 31711141, 2020). "BRCA1-deficient breast cancers with PTEN mutation generally had higher T cell-inflamed signature scores compared to BRCA1-proficient breast cancers and BRCA1-deficient breast cancers without PTEN mutation." (PMID 31022191, 2019). "For instance, genes like BRCA1, CDH1, RARB2, PTEN have all been reported to have abnormal methylation epigenetically modified DNA fragments in the promoter or exonic regions and such modifications have also been confirmed to participate in the tumorigenesis in breast cancer." (PMID 31480430, 2019). "In addition to cancer-associated variants in BRCA1/2 and non-BRCA genes in breast cancer, there have been reports of biallelic mutations in Australia, Italy, Denmark, Spain, Korea, and other Caucasian populations." (PMID 31658756, 2019). "Interestingly, BRCA1-, but not BRCA2-, deficient breast cancer was associated with higher PD-L1 (CD274) expression compared to BRCA-proficient breast cancers in both WSI and TCGA cohorts (PBRCA1 = 5.6 x 10−6 and 0.014, respectively." (PMID 31022191, 2019). "However, we found no changes in TAS levels in BRCA1– patients with breast cancer compared to controls." (PMID 31597313, 2019). "Interestingly, BRCA1-, but not BRCA2-, deficient breast cancers were observed to be associated with higher expression of PD-L1 and PD-1, and increased abundance of tumour-infiltrating immune cells involved in adaptive immune response." (PMID 31022191, 2019). "For example, 60.13% of the ‘Gene: BRCA1 or BRCA2’ subpopulation had breast cancer before age 50 years, with a mean onset age at 46.80 ± 11.87 years compared to 64% of the ‘Gene: PALB2’ subpopulation that had breast cancer before age 50 years, with a mean onset age at 49.20 ± 8.50 years." (PMID 30759220, 2019). "Indeed, we shown that BRCA1-deficient breast cancers with PTEN mutation, but not BRCA1-deficient breast cancers without PTEN mutation, to be associated with T cell-inflamed signature." (PMID 31022191, 2019). "A recent study suggests approximately a third of newly diagnosed breast cancer patients in the US are not offered BRCA1/BRCA2 genetic tests, despite the fact that the result may inform their treatment." (PMID 30689103, 2019). "Our data suggest that BRCA1 testing may be justified for families with multiple female breast cancers, breast and ovarian cancer or early-onset breast cancer and BRCA2 testing for families with male breast cancer from Pakistan." (PMID 31528241, 2019). "While the identification of a BRCA pathogenic variant constitutes a clear benefit for probands and their relatives, a proportion of at-risk families do not present pathogenic variants in BRCA1 or BRCA2 and their genetic risk of breast cancer remains unexplained." (PMID 31780696, 2019).
breast cancer (continued). "As expected based on PD-L1 and PD-1 expression and immune infiltrate profile, BRCA1-, but not BRCA2-, deficient breast cancers were associated with higher T cell-inflamed signature in WSI (P = 1.9 x 10−7 and 0.072, respectively) and TCGA (P = 8.0 x 10−3 and 0.95, respectively)." (PMID 31022191, 2019). "Breast cancer patients with BRCA1 germline mutation do not express ER, PR, and HER2 and share morphological, clinical, and molecular features and immunohistochemical and cytokeratin expression patterns like basal like breast cancers." (PMID 35582587, 2019). "However, both surprisingly and interestingly, hypoxia can significantly block SAHA-induced loss of stemness in the BRCA1-reconstituted HCC1937 cells, suggesting that hypoxia has the potential to disrupt the synergy between BRCA1 and SAHA in inducing breast cancer cell differentiation." (PMID 31273285, 2019). "Breast cancer cells lacking expression of functional BRCA1 are more sensitive to mTOR inhibitors." (PMID 31771139, 2019). "In addition to BRCA1 and BRCA2 genes, previous studies supported the contribution of other undetermined genetic factors to the aetiology and prognosis of prostate cancer in breast cancer-prone families." (PMID 31477094, 2019). "Similarly, BRCA1-, but not BRCA2-, breast cancers was also associated with higher PD-1 (PDCD1) expression compared to BRCA-proficient breast cancers in both WSI and TCGA cohorts (PBRCA1: 0.013 and 7.2 x 10−3, respectively." (PMID 31022191, 2019). "But we did not detect most frequent type of BRCA1/2 mutation in our cohort, the reason is perhaps that DCIS is less commonly in breast cancer, a large‐scale cohort study is required to obtain more precise information about founder mutations of DCIS patients in Japan." (PMID 30652428, 2019). "Therefore, we further investigated whether KPNA2 silencing induces apoptosis of breast cancer MDA-MB-231 cells upon radiation and disturbs the nuclear transport of BRCA1 molecules." (PMID 31212646, 2019). "Interestingly, BRCA1-, but not BRCA2-, deficient breast cancers were associated with increased expression of PD-L1 and PD-1, higher abundance of tumour-infiltrating immune cells, and enrichment of T cell-inflamed signature." (PMID 31022191, 2019). "We did not write specifically about BRCA1 or BRCA2, but “When analyzing your samples, we have discovered findings indicating that there could be a hereditary cause of your breast cancer." (PMID 29082482, 2018). "In addition, a higher proportion of survey responders with complete BRCA1/2 testing had a personal history of breast cancer (31.8% tested vs. 14.0% not tested, p < 0.01) and family history of ovarian cancer (8.7% tested vs. 4.4% not tested, p = 0.014)." (PMID 29514700, 2018). "Interestingly, chromosome 3 gain has not been observed in a BRCA1 driven murine breast cancer model, nor a KRAS driven model of non–small cell lung cancer while frequent partial gain of this chromosome was described in a MYC driven murine model of lymphoma." (PMID 29492199, 2018). "Another novel finding of this study is that BRCA1 expression is strongly associated with the high AHR-expressing ERα-negative subpopulation, indicating a possible implication of AHR in DNA repair in ERα-negative breast cancers." (PMID 29320557, 2018). "BRCA1/2 penetrance rates are high; results from prospective analysis of EMBRACE trial were recently reported and showed that the average cumulative risks, by age 70 years, for BRCA1 carriers were estimated to be 60% for breast cancer, 59% for ovarian cancer, and 83% for contralateral breast cancer." (PMID 29409476, 2018). "Gene expression studies of 17q25.3 have identified significant overexpression of 17q25.3 genes in BRCA1 mutated triple-negative breast cancer (TNBC) as compared with BRCA1 nonmutated TNBC, highlighting the important role that overexpressed sets of genes in this region may play in BC." (PMID 29871690, 2018).
breast cancer (continued). "The concept that a luminal cell may be the cell-of-origin for basal-type breast cancer is not new and has been previously proposed in the context of BRCA1-driven disease." (PMID 29795293, 2018). "Females of these Brca1 GEMM do not form mammary tumors in the first 10 months of life." (PMID 29651417, 2018). "Both G5337A and A3199G polymorphisms present in BRCA1 and BRCA2 genes respectively, have not yet been reported as deleterious mutations (i.e. mutations directly involved in the development of breast cancer), and in consequence they should be considered as benign polymorphisms." (PMID 29021639, 2017). "In this study, we evaluated NHERF1, BRCA1 and PARP1 protein expression by means of immuno-histochemistry in a retrospective series of invasive BC including a subgroup of triple negative breast cancers (TNBCs)." (PMID 29029467, 2017). "Interestingly, stable overexpression of β-hCG in BRCA1 mutant but not wild-type breast cancer cells results in the formation of spheres even on monolayer cultures." (PMID 28869585, 2017). "These tumor-suppressive actions may be specific for BRCA1, as polymorphisms in HMMR modify breast cancer risk associated with mutations in BRCA1 but not BRCA2." (PMID 28427147, 2017). "Another mouse model of BRCA1-deficiency in either luminal progenitor cells or basal stem cells demonstrated that deletion of BRCA1 in the luminal progenitor cells, rather than the basal stem cells, phenotypically and histologically induced basal-like breast cancers." (PMID 27793013, 2017). "Herein, we used two distinct methods of BRCA1 labeling (IHC versus dual IF) and two different antibodies one of which is MS110 (AB-1) that has been shown to be the most reliable, accurate, and reproducible antibody for immunolocalization of BRCA1 on breast cancer paraffin-embedded tissues." (PMID 28863181, 2017). "The PRS based on SNPs associated with ER-negative disease in the general population displayed a much stronger association with overall breast cancer risk for BRCA1 carriers than the ER-positive PRS, consistent with the observation that the predominant tumor subtype in BRCA1 carriers is ER negative." (PMID 28376175, 2017). "Interactions between the IGF1 and BRCA1 signaling pathways are not restricted to breast cancer." (PMID 28706506, 2017). "Our data showed a trend towards having lower ER and PR immunoreactive scores in tumors that have low BRCA1 expression which is in agreement with previous studies showing BRCA1-related breast cancers are more frequently ER negative than nonhereditary breast cancers." (PMID 28863181, 2017). "Also, wild-type but not mutant BRCA1 transcriptionally regulates the expression of β-hCG and knockdown of wild-type BRCA1 induces β-hCG in different breast cancer cell lines." (PMID 28869585, 2017). "All the carriers were BRCA1/2 negative and one patient had a family history of breast cancer." (PMID 28874143, 2017).
breast cancer (continued). "Almost 2000 variants have been found in the two genes (BRCA1 and BRCA2) and, for numerous; it is yet not recognized whether or not they enhance prevalence of breast cancer." (PMID 28969709, 2017). "In BRCA1/2 families, early-onset breast cancer (BrCa) cases may be also observed among non-carrier relatives." (PMID 28199346, 2017). "Conditional knock out of either Brca1 or Bard1 in murine mammary epithelial cells led to the development of mammary carcinomas that are indistinguishable from each other, and the BRCA1 C61G mutant that abrogates BARD1 binding failed to suppress mammary tumor development in mice." (PMID 28398198, 2017). "However, the possibility that this mechanism explain the BRCA1 silencing observed in breast cancer cells treated with ethanol, not yet been explored." (PMID 26877711, 2016). "The majority of families with smaller aggregations of breast cancer do not yet have demonstrable underlying genetic defects and the majority of carriers of pathogenic mutations in BRCA1 and BRCA2 do not have strong aggregation of breast cancer in their families." (PMID 27087880, 2016). "Current models predict either the risk of carrying a high-risk genetic mutation such as BRCA1/2 (e.g., Claus model, BOADICEA, and BRCAPRO) or the risk of developing breast cancer over time with or without such a mutation (e.g., Gail model, BOADICEA, Rosner-Colditz model, and Tyrer-Cuzick model)." (PMID 27645219, 2016). "Platinum-based treatments alone or in combination have generated interest in treating TNBC, due to lack of treatment options for this subtype of breast cancer, and their use has been supported by the strong association of TNBC tumors with germline mutations in the BRCA1 gene." (PMID 26799586, 2016). "As the highest demethylation of BRCA1 promoter coinciding with the highest increase in BRCA1 expression was detected for combinations of TDE-I with sgRNA-2 or sgRNA-4, we assessed the effects of these combinations in another cell line, namely MCF7 breast cancer cells." (PMID 27356740, 2016). "However, besides careful monitoring and life planning followed by mastectomy—in terms of BRCA1 carriers—there is no current drug that is suitable for the prevention of breast cancer." (PMID 27881737, 2016). "We categorized our patients into two age groups below 50 years and above or equal to 50 years; there was a nonsignificant increase in BRCA1 promoter methylation of breast cancer tissue specimens in older women compared with younger patients (70.6% versus 29.4%, resp)." (PMID 27413552, 2016). "Ubc9 binding site mutations, as well as cancer-predisposing mutation in the BRCA1 RING domain (C61G), disrupted the ability to modulate Ubc9-mediated estrogen-induced ER-α transcriptional activity in breast cancer cells but did not disrupt SUMO-1 binding nor auto ubiquitination activity of BRCA1." (PMID 28164176, 2016). "The discovery of the BRCA1/NEAT1/miR-129-5p/WNT4 axis and the pivotal roles of WNT4 in WNT signaling activation as well as in the enhancement of BCSC generation suggest that WNT signaling is a potential therapeutic target for breast cancer with alterations in this signaling axis." (PMID 27556296, 2016). "Currently, an effective treatment regimen targeting BRCA1-defective breast cancers is absent." (PMID 27220670, 2016). "Studies have shown that tamoxifen might also be effective in BRCA1 and BRCA2 mutation carriers in respect to reducing CBC risk consistent with our finding of risk reductions regardless of family history of breast cancer." (PMID 27400983, 2016).